AVP (arginine vasopressin)
Diseases named in the same sentence as AVP in open-access papers (continued):
Sharing a sentence is not in itself a finding about the gene and the disease.
Anxiety (continued). "Taken together, these results support the hypothesis that maternal AVP and OXT treatment have context- and behavior-specific effects on peripheral IFNγ levels and perseverative, anxiety, and social behaviors in female offspring of early-life social stress-exposed dams." (PMID 28018290, 2016). "Given that AVP and the closely related neuropeptide oxytocin (OXT) modulate social behavior as well as anxiety-like behavior, we hypothesized that these neuropeptides may regulate social play behavior differently in novel (novel cage) as opposed to familiar (home cage) social environments." (PMID 24982623, 2014). "Collectively, however, these data suggest that AVP within the PVN may influence anxiety-like states primarily in males, while not affecting their ability to socially interact with male and female conspecifics, suggesting a lack of linkage between social- and non-social anxiety states." (PMID 36860367, 2023). "More specifically, BNST AVP knockdown in male, but not female, mice reduced investigation and communicative behaviours directed toward same‐sex conspecifics as well as male sexual behaviour, without changing offensive attacks, anxiety‐related behaviours, and overall activity." (PMID 34978098, 2022). "In addition to these classic “anxiety molecules,” recent years have seen a rise in studies investigating neuropeptides such as oxytocin and arginine vasopressin (AVP) to help better understand negative emotionality and personality (for an overview see Montag and Reuter, 2014)." (PMID 25852497, 2015). "Anxiety, stress, and positive or negative stimuli drive the synthesis and release of OXT and AVP from neurons in the hypothalamic supraoptic nucleus (SON), paraventricular nucleus (PVN), or limbic system regions." (PMID 36430254, 2022). "Indeed, if increased ratings of other female faces are part of a “tend and befriend” stress responses strategy, particularly in women, then AVP’s behavioral influences may not be directly related to reward and/or positive affect, but rather to stress/anxiety reduction." (PMID 28871239, 2017). "AVP has been shown to influence verbal WM, but not always, and there is no agreement whether its influence is direct and specific (e.g., through brain regions heavily involved in memory such as the hippocampus), or mediated by general factors such as anxiety, attention and arousal." (PMID 24151474, 2013). "The lesion results also diverge from some correlational studies showing that PVN AVP-ir positively correlates with levels of anxiety-like behavior in rats and mice, and that reductions of PVN AVP expression correlated with increases in anxiety in juvenile male, but not female, rats." (PMID 36860367, 2023).
Polyuria (85 papers, 2006 to 2026). An increased rate of urine production. "AVP measurement in response to osmotic stimulation has therefore long been recommended in the diagnostic evaluation of patients with polyuria polydipsia (see subsequent section on “Use of Water Deprivation Tests”)." (PMID 39148427, 2025). "Concurrently, CDI – resulting from AVP deficiency – impaired renal water reabsorption, further exacerbating polyuria and hyperosmolality." (PMID 41211065, 2025). "Hypercalcemia is known to cause reversible arginine vasopressin resistance (nephrogenic diabetes insipidus); consequently, the possibility of polyuria being secondary to this condition was entertained." (PMID 40123924, 2025). "AVP loss typically presents with the polyuria and polydipsia of CDI, whereas OXT deficiency manifests more subtly through alterations in emotional regulation, feeding behavior, and social cognition." (PMID 41614746, 2025). "Dexmedetomidine is an α-agonist that blocks the release of AVP and theoretically causes intraoperative polyuria." (PMID 38956694, 2024). "Neuron-specific conditional KO (cKO) of Wnk1 caused polyuria with decreased urine osmolality that persisted in water restriction and blunted water restriction–induced AVP release." (PMID 37071482, 2023). "Familial neurohypophysial diabetes insipidus (FNDI), commonly caused by autosomal dominant arginine vasopressin (AVP) mutations, is a rare condition in which vasopressin fails in regulating body’s level of water with final polyuria and polydipsia." (PMID 34319541, 2021). "Although we did not see significant differences between survival agents, dexmedetomidine has been reported to cause polyuria through blockage of arginine-vasopressin release." (PMID 32647241, 2020). "It is widely accepted that nocturnal polyuria in the majority of children is related to an insufficient nocturnal increase in antidiuretic hormone, i.e., arginine vasopressin (AVP), causing a high diuresis rate with low osmolality overnight." (PMID 27071997, 2017). "The most prominent renal phenotype in BBS patients is polyuria; a phenotype which was linked to a defective AVP signalling cascade." (PMID 26273430, 2015). "This limits the ability to diagnose AVP disorders as the cause of polyuria with certainty." (PMID 40851690, 2025). "Additionally, ifosfamide can also cause arginine vasopressin resistance, which is a hereditary or acquired condition characterized by polyuria due to the inability of the collecting duct to concentrate urine." (PMID 40291173, 2025). "Isolated DI centralis may occur as an endocrine symptom and is characterized by deficient secretion of arginine vasopressin (AVP), leading to clinical symptoms of polyuria and polydipsia." (PMID 35897050, 2022). "Additionally, mice with SEL1L deficiency in arginine vasopressin (AVP) neurons were demonstrated to develop polyuria and polydipsia, suggesting the pathophysiological importance of the SEL1L/HRD1 ERAD protein quality-control machinery in health and disease." (PMID 30282948, 2018). "Patients who have symptoms of polyuria, nocturia, or polydipsia are candidates for further evaluation of a possible arginine vasopressin-related polyuria (AVP-D or AVP-R)." (PMID 39148427, 2025). "Nocturnal polyuria in conjunction with an abnormal circadian release of antidiuretic hormone or arginine vasopressin is a major contributing factor to NE." (PMID 37829504, 2023). "As reported, 80% to 90% of the magnocellular AVP neurons in the hypothalamus must be destroyed to produce polyuria and polydipsia, indicating extensive destruction of the AVP magnocellular neuron cell bodies is needed to induce DI." (PMID 37988666, 2023). "Nephrogenic diabetes insipidus (NDI) is characterized by impaired arginine vasopressin (AVP)-induced water reabsorption in the kidney, leading to polyuria, polydipsia, and hypernatremia." (PMID 34512542, 2021).
Polyuria (continued). "Both urinary ATP and purinergic‐mediated prostanoid (PGE2) levels were elevated in UT‐A1/A3 KO mice suggesting that, like some other known models of AVP‐resistant polyuria, purinergic signaling is increased in UT‐A1/A3 KO mice." (PMID 33369887, 2021). "Because P2Y2 inhibits AVP‐stimulated transport by dampening cAMP synthesis, we suspected that, similar to other models of AVP‐resistant polyuria, purinergic signaling is increased in UT‐A1/A3 KO mice." (PMID 33369887, 2021). "Current mechanisms under investigation as potential targets for polyuria include arginine vasopressin (AVP), a hormone secreted from the posterior pituitary which controls fluid homeostasis in the body." (PMID 29385166, 2018). "Possibly, the decrease in plasma apelin levels of patients with CDI is insufficient as compared to the decrease of AVP/copeptin to reestablish a balance between the antidiuretic effect of AVP and the diuretic effect of apelin, resulting in polyuria." (PMID 28620355, 2017). "Congenital nephrogenic diabetes insipidus (CNDI) is a disorder characterized by polyuria and polydipsia due to renal resistance to the antidiuretic hormone, arginine vasopressin (AVP)." (PMID 26714855, 2015). "Polyuria and polydipsia typically develop in childhood due to a progressive decline in AVP secretion and selective degeneration of AVP-producing neurons." (PMID 24616780, 2013). "The hypothesis label 'dual hormone suppression' (attenuated nocturnal AVP signal plus estradiol decline) may provide a mechanistic substrate for cold-exacerbated nocturnal polyuria, while an estrogen-TRPM8 axis may amplify cold-evoked urgency." (PMID 41829995, 2026). "Similarly, one study investigated plasma AVP response to intravenous infusion of 20% hypertonic saline for 2 h in 18 dogs with polyuria that had been present in most cases since a young age." (PMID 40160705, 2025). "It is well described that at least some children with nocturnal polyuria have increased sodium excretion during wet nights, and that nocturnal polyuria is not only explained by AVP alterations, which is in line with our findings of increased but not significant sodium excretion." (PMID 37140712, 2023). "It has been documented that nocturnal polyuria is common in children with NE and can either be due to inadequate nocturnal arginine vasopressin (AVP) secretion during sleep or due to factors beyond renal water handling, such as osmotic diuresis and natriuresis." (PMID 37140712, 2023). "Day–night reversal, such as decreased secretion of arginine vasopressin and increased blood pressure at night, may be present in older patients with nocturnal polyuria." (PMID 35629972, 2022). "Besides, four guidelines recommended arginine vasopressin which was mainly adopted for treating polyuria at night." (PMID 32269526, 2020). "The sustained suppression of circulating AVP in response to overdrinking enhances urinary free water excretion and teleologically represents the most appropriate renal adaptation to a constant fluid intake load (polydipsia = polyuria)." (PMID 31284689, 2019). "Among these, the prevalence of GDI is approximately 1 in 30,000 pregnancies, and patients with GDI are characterized in pregnancy by polyuria and polydipsia due to placental overproduction of vasopressinase, which is expressed in placental trophoblasts and degrades arginine vasopressin (AVP)." (PMID 29378555, 2018). "However, since in NDI AVP is unable to exert its antidiuretic effect at the kidney level, it is likely that only apelin exerts its deleterious effect, which results in polyuria." (PMID 28620355, 2017). "In humans, CDI is characterized by decreased release of AVP, resulting in polyuria." (PMID 27732637, 2016). "All together these data demonstrate that the specific inactivation of Bbs10 in the renal epithelial cells does not induce polyuria and the associated high AVP circulating levels." (PMID 26273430, 2015).
Polyuria (continued). "AVP-deficient animals showed reduced theta activity compared to their wild-type littermates, which was temporarily normalized by icv desglycinamide AVP administration (without a significant influence on polydipsia and polyuria)." (PMID 36555107, 2022). "In addition, regardless of the etiology of PPS, polyuria itself can trigger abnormality in urine concentrating ability due to loss of medullary tonicity and downregulate AVP release." (PMID 33916272, 2021). "Urine AQP2 excretion in dogs can still be used as a prognostic tool to differentiate polyuria diseases such as central or NDI, inappropriate arginine vasopressin protein release, and primary polydipsia." (PMID 34903939, 2021). "Congenital Nephrogenic Diabetes Insipidus (NDI) is characterized by impaired water resorption in the collecting duct due to insensitivity to arginine vasopressin (AVP) of principal cells, leading to polyuria and polydipsia." (PMID 34177810, 2021). "Together with the observation that AVP-Cre; nCTG mice possess fewer AVP+ neurons in the PVH, we hypothesized that these mice evoked polyuria, presumably accompanied by polydipsia." (PMID 40354365, 2025). "Unlike AVP or ACTH deficiency, OXT-D typically lacks polyuria, polydipsia or electrolyte imbalance, and emotional–social symptoms often persist despite normalization of other hormonal axes." (PMID 41614746, 2025). "Taken together, the results from this study provide further evidence that SCI is a complex and progressive injury, which includes changes in various metabolic peptides (AVP, ANP, V2R, NPRA, and ENaC) that contribute to the development and maintenance of SCI-induced polyuria." (PMID 34901942, 2021). "This circadian rhythm in AVP levels is functionally important, because the absence of an AVP surge during the late-sleep stage resulted in polyuria and disrupted sleep." (PMID 30455627, 2018). "Neither defect of AVP release (central polydipsia) can explain the polyuria of β3-AR−/− mice because these mice show normal urine-concentrating abilities under a water deprivation challenge." (PMID 27206969, 2016). "Additionally, patients with AVP-D do not develop symptoms other than polyuria and polydipsia (e.g., dehydration, nocturia, etc.)until their hypothalamic secretion of AVP drops below 15%, which occurs relatively late in the disease course." (PMID 40075671, 2025). "Urinary ANP and serum AVP levels for the various SCI animal time-point groups were significantly altered in the direction that would have produced polyuria at various 14- to 42-dpi time points, but did not match the onset (7 dpi) and duration of the overproduction of urine that was measured." (PMID 34901942, 2021). "While aging-related decline in AVP secretion is a well-established contributor, emerging evidence implicates ANP as a key mediator of nocturnal polyuria in non-cardiac populations." (PMID 40873792, 2025). "Polyuria and polydipsia are the hallmarks of CDI, which is brought on by a lack of arginine vasopressin (AVP), an antidiuretic hormone that stimulates the reabsorption of free water by acting on V2 receptors in the kidney." (PMID 38555457, 2024). "Absence of the anti-diuretic hormone, arginine vasopressin (AVP), facilitates copious free water urinary excretion (polyuria) in equal volumes to polydipsia to maintain plasma tonicity within normal physiological limits." (PMID 31284689, 2019).
Polydipsia (68 papers, 2006 to 2026). Excessive thirst manifested by excessive fluid intake. "AVP production and secretion are tightly regulated by plasma osmolality, maintaining water balance homeostasis, whereas AVP system impairment results in AVP deficiency (AVP-D), characterized by polydipsia and polyuria." (PMID 40737512, 2026). "It is characterized by hypotonic polyuria, polydipsia, and dehydration risk, and is diagnosed by distinguishing it from AVP resistance and primary polydipsia, with copeptin-based tests providing high diagnostic accuracy." (PMID 41363127, 2026). "DI is characterized by impaired renal water reabsorption, either due to a deficiency of AVP or renal resistance to its action, resulting in hypotonic polyuria and polydipsia." (PMID 41211065, 2025). "CDI is a rare but potentially life-threatening condition caused by a deficiency in AVP, resulting in hypotonic polyuria and compensatory polydipsia." (PMID 40827185, 2025). "AVP-D due to a deficiency in AVP (arginine vasopressin) is characterized by hypotonic, dilute polyuria (low urine osmolality), polydipsia, elevated plasma osmolality, and sometimes hypernatremia." (PMID 40075671, 2025). "AVP deficiency leads to the inability to concentrate urine, resulting in hypotonic polyuria and polydipsia." (PMID 39544593, 2024). "If after the water deprivation test the urinary osmolality remains between 300 and 800 mOsm/kg, the cause of polyuria may be partial AVP deficiency, partial AVP resistance, or primary polydipsia." (PMID 39458112, 2024). "It is important to differentiate between AVP resistance, AVP deficiency, and primary polydipsia as their treatment differs and incorrect management could have dire consequences." (PMID 37859988, 2023). "The indirect water deprivation test is the gold standard to differentiate between arginine vasopressin deficiency (AVP‐D), arginine vasopressin resistance (AVP‐R), and psychogenic polydipsia (PP) in patients with polydipsia‐polyuria syndrome." (PMID 39639680, 2025). "CDI is characterised by hypotonic polyuria and polydipsia resulting from decreased concentrations of arginine vasopressin (AVP), also known as antidiuretic hormone (ADH)." (PMID 35172866, 2022). "Previous studies have demonstrated that viral delivery of AVP cDNA behind the ubiquitous CMV promoter to the SON ameliorates the polydipsia, polyuria, and decreased plasma osmolality of adult male Hom rats." (PMID 31160697, 2019). "However, their blood lacks AVP (which is produced in magnocellular, neurosecretory hypothalamic cells); therefore, they develop central diabetes insipidus with polydipsia and polyuria." (PMID 36555107, 2022). "Furthermore, rescue of AVP production in this pathway ameliorated the polydipsia of adolescent Brattleboro rats." (PMID 31160697, 2019). "Altered peripheral AVP and elevated levels of polydipsia have been noted in schizophrenics." (PMID 31160697, 2019). "Whether or not this reverse in osmotic thresholds for thirst and AVP stimulation is a cause or effect of psychogenic polydipsia remains unclear." (PMID 31284689, 2019). "Clinical manifestations of CDI include polydipsia induced by lack of AVP." (PMID 31049061, 2019).